H2AX (H2A.X variant histone)
Diseases named in the same sentence as H2AX in open-access papers (continued):
Sharing a sentence is not in itself a finding about the gene and the disease.
tumor (continued). "In the present study, we aimed to investigate alterations of the tumor stroma in SH-HCCs, comparing the expression of CAFs, HSCs, senescence-associated proteins, and SASP factors (p21Waf1/Cif1, γ-H2AX, and IL-6) between SH-HCCs and C-HCCs." (PMID 28273155, 2017). "Significant increase in the level of DSBs, as evaluated by immunofluorescence staining for γ-H2AX, was also detected in tumor xenografts from treated mice." (PMID 28981112, 2017). "Kinetics of DNA damage after radiotherapy was assessed in eight dogs using repeated in vivo samples of tumor and co-irradiated normal tissue analyzed with comet assay and phosphorylated H2AX (γH2AX) immunohistochemistry." (PMID 28587165, 2017). "The increase in γ-H2AX compared to vehicle was even more significant when tumor-bearing mice were treated were a combination of CPT11 and the PARP inhibitor olaparib." (PMID 28158293, 2017). "When compared with other groups, an increased number of γ-H2AX positive cells was observed in tumor tissue derived from mice treated with PDMP + RT." (PMID 28797171, 2017). "We thus sought to define the transcriptomic signatures enabling us to distinguish the tumours with high‐ versus low‐H2AX protein levels (Welch's t‐test) in aggressive BC subtype." (PMID 27006338, 2016). "Immunoreactivity of γ-H2AX indicating occurrence and maintenance of DNA damage in the tumor specimen was evaluated." (PMID 27386977, 2016). "The expression of γ-H2AX is much higher in the tumor tissue generated from Huh7 cells (Huh7-vector) than that in the Huh7-TIPE2 tumor tissues." (PMID 27696294, 2016). "Infection of tumor cells with rotavirus isolates resulted in a significant percentage of γ-H2AX-positive cells." (PMID 26828934, 2016). "Quantified immunohistofluorescence data showed that there was a significant correlation between decreased Ku70 and increased γ-H2AX in castrated PCa tumor tissue." (PMID 27487144, 2016). "Both 90Y-ITGA6B4 treatment groups showed reduction in tumor volumes (P < 0.04), decreased cell proliferation marker Ki-67-positive cells and increased DNA damage marker p-H2AX-positive cells, compared with the other groups." (PMID 27246980, 2016). "The accumulation of breaks in tumor cells is deduced from the high amount of cells with γ-H2AX immunofluorescence." (PMID 27331622, 2016). "H2AX protein levels and γ‐H2AX were significantly reduced in residual tumours of TN patients after chemotherapy." (PMID 27006338, 2016). "H2AX downregulation accounted for the decrease in γ‐H2AX, as the γ‐H2AX/H2AX ratio remained equivalent, confirming, in human tumours, the observations we made in genetic models of chronic oxidative stress." (PMID 27006338, 2016). "Increase in phospho-ATM levels was detected following CDV exposure and higher levels of γ-H2AX (a quantitative marker of double-strand breaks) were measured in tumor cells compared to normal cells." (PMID 27331622, 2016). "Consistently, the expression of several NRF2‐target genes was significantly downregulated in tumours with major‐H2AX decrease, compared to tumours with minor‐H2AX decrease." (PMID 27006338, 2016). "NRF2 protein levels decreased significantly after chemotherapy in tumours characterized by major‐H2AX decrease, while it remained unchanged in tumours with minor‐H2AX decrease." (PMID 27006338, 2016). "For assessment of DNAdamage response in the tumor cells, γ-H2AX levels were analysed byimmunohistochemical method." (PMID 26189912, 2015). "Compared to the NC group, H2AX knockdown resulted in a significant decrease in tumor size and weight (P<0.001)." (PMID 25537504, 2015). "Tumor tissue was prepared as frozen sections for γ-H2AX detection and for a TUNEL assay to detect apoptosis." (PMID 26462155, 2015). "And the results showed that γ-H2AX levels were higher in tumor tissues of patients with post-LT HCC recurrence (n = 24) in comparison to patients with no-recurrence (n = 33) (p < 0.001)." (PMID 25537504, 2015).
tumor (continued). "Kaplan–Meier analysis revealed that HCC tissues with high expression of γ-H2AX had either worse overall survival (p = 0.002) or shorter tumor-free survival (p < 0.001)." (PMID 25537504, 2015). "The results showed that γ-H2AX levels were higher in tumor tissues of patients than peritumoral tissues (p = 0.001) and normal tissues (p = 0.001)." (PMID 25537504, 2015). "We assessed the RAD51 response in human tumour cells transfected with CBLC siRNA, as well as the formation of γH2AX foci, a marker of histone H2AX phosphorylation that is associated with DNA DSB formation." (PMID 25883215, 2015). "For patients whose tumor had high levels of both γ-H2AX and HIF-1α had worse over-all survival, so as with high levels of both γ-H2AXand EGFR." (PMID 25537504, 2015). "Decrease in tumor growth correlated with an increase in double strand DNA breaks as measured by γ-H2AX phosphorylation." (PMID 25774912, 2015). "Exposure to afatinib also suppressed IR-induced elevations of γ-H2AX foci formation and reduced DNA-pKcs expression in these tumor tissues." (PMID 25714021, 2015). "The lower absolute number of basal γ-H2AX foci in Cal33 IR compared to the parental Cal33 is in line with the significantly higher in vitro radioresistance of Cal33 IR and its increased tumor volume growth in vivo compared to the parental Cal33 cells." (PMID 26460734, 2015). "At 24 h, dose dependent γ-H2AX foci were more numerous than at 2 h, and greater in tumours than in peripheral blood mononuclear cells." (PMID 26282406, 2015). "Significantly increased IR-induced γ-H2AX foci in tumor specimens persisted at 1, 6, and 24 hours with PSMA1 knockdown compared to control, indicating delayed DNA DSB repair." (PMID 24040035, 2013). "Increased frequencies of γ-H2AX foci have been extensively used to measure DNA damage by physical agents, oncogenes, or inactive tumor suppressors." (PMID 23886499, 2013). "Dexrazoxane alone also increased the levels of γ-H2AX in tumor cells, while Mito-T alone appeared to induce levels of DNA DSBs in the tumor comparable to that of doxorubicin." (PMID 23940596, 2013). "As suggested by a referee, we performed correlation analysis between tumor stage and the expression of γ-H2AX and 53BP1 foci." (PMID 23617930, 2013). "This study explores the relationship between the clinical radiosensitivity of tumor patients and the expression/induction of γ-H2AX and 53BP1 in vitro." (PMID 23617930, 2013). "Specifically, Mito-T alone showed more γ-H2AX-marked DNA double-stranded breaks than dexrazoxane in the presence of comparable apoptosis in the tumor." (PMID 23940596, 2013). "Several studies have shown that elevated γ-H2AX in premalignant lesions have a tumor-suppressing function promoting cell cycle arrest and senescence which has also been demonstrated in knock-out mice." (PMID 23029205, 2012). "In both A549 and H1299 xenografts we detected increased levels of phosphorylated H2AX (γH2AX) in the irradiated tumours compared to untreated control tumours that were significantly higher in H1299 xenografts." (PMID 22607554, 2012). "Enhanced levels of H2AX have also been described in human tumours 24 h after a clinical dose of radiotherapy of 2 Gy." (PMID 22607554, 2012). "Based on these results, we ultimately tested individual compounds for increased persistence of γ-H2AX and decreased tumor cell viability." (PMID 22768044, 2012). "Compared to corresponding normal tissue samples, miR-24-2 was low in tumors and was relatively higher in stage I and lower in stages II and III tumor tissue samples, with an inverse relation between mir-24-2 and H2AX mRNA expression." (PMID 21463514, 2011). "Media conditioned on cultures of both aging and tumor cells were found to induce elevated levels of γ-H2AX foci in normal cells." (PMID 21325706, 2011).
tumor (continued). "The study therefore suggested BCL-2 as a possible novel cellular target of miR-24-2 and confirmed H2AX regulation by miR-24-2 in proliferating cell lines and in tumor samples." (PMID 21463514, 2011). "To investigate potential mechanisms behind radiosensitization of tumor cells by T-oligo, we next examined the levels of nuclear-foci containing phosphorylated H2AX (H2AX), a modification that occurs at sites of DNA breaks." (PMID 20846433, 2010). "Yuet al. reported that tumor cell cultures exhibited large numbers of endogenousγ-H2AX foci per cell, sometimes equivalent to several Gy of ionizingradiation." (PMID 20157510, 2009). "In contrast to ATM-/- mice which die of T cell lymphomas with clonal translocations, 53BP1-/- and H2AX-/- mice are mildly tumor prone." (PMID 16945145, 2006). "H2AX, a critical component of the DNA damage response pathway, is associated with HCC radioresistance, while TF, a key regulator of iron metabolism, influences tumor growth and oxidative stress in HCC." (PMID 40307890, 2025). "Additionally, mild intracytoplasmic Nop10 and H2AX expressions were observed in neurons around the tumor mass in brain tissues." (PMID 39821858, 2025). "The findings presented in the current study also demonstrate a dose-dependent reduction in Ki67, Nop10, and H2AX expressions in tumor cells around blood vessels, alongside GFAP expression, following treatment with BA in astrocytes surrounding the tumors in rat GBM model." (PMID 39821858, 2025). "Therefore, we also detected the levels of γ-H2AX and ROS in tumor tissues by means of immunofluorescence." (PMID 40944197, 2025). "Furthermore, in an orthotopic CCA model, Aurkine 16 significantly reduced tumor volumes compared to controls, along with an increase in p-H2AX+ cells and enhanced infiltration of CD8+ and CD4+ T cells into tumors." (PMID 40324694, 2025). "The findings indicate that abemaciclib, in combination with RT, enhanced tumor cell radiosensitivity, enhanced gamma-H2AX phosphorylation, reduced AKT phosphorylation, attenuated PI3K/mTOR signaling, alleviated radiation-induced vasculogenesis, and enhanced tumor growth delay." (PMID 40035822, 2025). "In addition, DNA damage (γ-H2AX) fluorescence staining suggested that UHDR-RT notably increased the level of DNA damage by 2-fold in tumor tissues compared with Conv-RT." (PMID 40032871, 2025). "Additionally, to assess DNA damage, IF staining of γ-H2AX was performed on tumor samples from each treatment group." (PMID 40963930, 2025). "Moreover, compared to other treatments, the immunofluorescence results of tumor sections from mice in the RT+MnBTC-Ru treatment group show a significant decrease in Ki67 expression, along with a significant increase in γ-H2AX expression." (PMID 40819134, 2025). "In our study cohort, we could only find a trend toward higher tumor stages in tumors with high γ-H2AX expression (p = 0.076)." (PMID 38502354, 2024). "We therefore propose that caution is needed in order to consider H2AX as a tumour suppressor." (PMID 38402225, 2024). "Interventions targeting pathways that alter H2AX expression could be demonstrated to influence the survival of tumor cells." (PMID 38502354, 2024). "Moreover, such reduction in tumor proliferation was caused by the induction of DNA damage as corroborated by the in vivo phosphorylation of CHK2 and Histone H2AX." (PMID 39125297, 2024). "This suggests that patients with low γ-H2AX expression levels in their tumor cells might derive greater benefit from chemoradiotherapy." (PMID 38502354, 2024). "Furthermore, compounds 5e and 5p activated the LC3 signaling pathway, inducing autophagy, and triggered the γ-H2AX signaling pathway, resulting in DNA damage in tumor cells." (PMID 38675599, 2024).
tumor (continued). "Based on these results, we selected the hypothesis that the chemotherapy resensitization by the ATMi could be particularly important in tumours which have lost H2AX." (PMID 38789420, 2024). "Furthermore, both compounds activated the LC3 signaling pathway, inducing autophagy, and the γ-H2AX signaling pathway, inducing DNA damage in Huh7 tumor cells." (PMID 38675599, 2024). "To validate this hypothesis, we monitored the changes in γ‐H2AX fluorescence foci within MB49 tumor cell nuclei after RT and observed a significant increase of such foci in the IR‐TAM@Alb pre‐treated group compared with other groups subjected to RT." (PMID 38715382, 2024). "Histone H2AX has a known role in DNA damage repair but interestingly, its loss is associated with resistance to poly(ADP-ribose) polymerase (PARP) inhibition in BRCA-deficient tumours." (PMID 38789420, 2024). "Therefore, H2AX is considered an anti-oncogenic barrier and has been proposed as a tumour suppressor." (PMID 38402225, 2024). "Given that γ-H2AX plays a crucial role in the physiological DNA repair system, we propose the evaluation of γ-H2AX expression as a potential biomarker for tumor response in future clinical trials of targeted treatments that interfere with the DNA repair system." (PMID 38502354, 2024). "A depletion of H2AX results in an inhibited apoptotic effect of imatinib on the tumor cells." (PMID 38502354, 2024). "However, γ-H2AX does not only correlate with worse patient survival and higher tumor stages, but also with specific tumor subtypes." (PMID 38502354, 2024). "Therefore, although H2AX is thought to act as a tumour suppressor and our results show that it contributes to homeostasis, they also indicate that it is required for the development of cancer." (PMID 38402225, 2024). "Finally, by western blot, we observed a significant increase of cCASP3 and γ H2AX in the tumor mass of Lestaurtinib treated mice, compared to DMSO treated mice." (PMID 37404750, 2023). "Moreover, the combination of UNC0379 and cisplatin substantially increased levels of γ-H2AX protein in subcutaneous tumor tissues, indicating an increase in DNA breaks." (PMID 37308924, 2023). "Moreover, DNA damage indicated by γ-H2AX staining in tumour tissues was increased by CREKA-lipo-anti-IFNγ treatment, which was inhibited by lactate treatment." (PMID 37056922, 2023). "Additionally, this combined treatment also largely inhibited TMZ-induced AMPK activation, RRM1 pT52 levels and substantially enhanced the levels of γ-H2AX and apoptosis in tumor tissues." (PMID 37737247, 2023). "Researchers discovered that the decay of 223RaCl2 results in the formation of track-like patterns of DDR proteins, mainly 53BP1 (known as α-tracks) and gamma-H2AX (γ-H2AX) foci, in both peripheral blood mononuclear cells and tumor cells in patients with prostate cancer (PCa) treated with 223RaCl2." (PMID 38140100, 2023). "Representative histology images of tumors stained for myc-tag, γ-H2AX, ki67, and H&E as well as tumor size show that BRG1-BRD overexpression in oNIS-expressing cells suppresses cancer cell proliferation and increases DNA DSBs, which enhances the effect of I-131 radiotherapy." (PMID 36769088, 2023). "The immunohistochemical results of Ki-67 and γ-H2AX demonstrated that the combination of celecoxib treatment with radiation resulted in stronger growth inhibition and apoptosis of tumor cells in GSCs derived xenografts compared with celecoxib or radiation treatment alone." (PMID 37438359, 2023).
tumor (continued). "Cell genome stability is maintained by DNA damage response by integrally coordinating DNA repair activity, cell cycle checkpoint, γ‐H2AX signalling and apoptosis program, all of which may greatly affect the therapeutic effect and tumour response to irinotecan." (PMID 35187743, 2022). "In addition to measuring treatment response with tumor volume, γ-H2AX IHC staining was performed on all tumors at the completion of treatment." (PMID 35046420, 2022). "DOX treatment-induced drug accumulation (determined by DOX fluorescence in individual cells) and DNA damage (indicated by phosphorylated histone γ-H2AX expression) in tumour cells, which could be attenuated by the addition of fibroblasts to the cultures." (PMID 36207295, 2022). "In addition, PLA2 knockdown suppressed MCM2 expression and increased the γ‐H2AX protein level in tumour tissues." (PMID 35166019, 2022). "Moreover, after the drug combination treatment, we found that TXNIP, Bax, and γ-H2AX expressions were upregulated while the bcl-2 and Ki67 expressions were downregulated in the tumor sections of nude mice." (PMID 35414060, 2022). "In addition, we performed IHC analysis on the same human tumor tissues for γ-H2AX and Ki-67 expression and compared the γ-H2AX and Ki-67 expression status (measured by IHC) from human tumor samples with negative and positive TS expression." (PMID 36048542, 2022). "In addition, a strong DNA damage increase was also detected in SR‐4835‐treated CRC cells and HCT116 subcutaneous tumours from either SR‐4835‐treatment or the CDK12‐knockdown group as reflected by the protein levels of γ‐H2AX." (PMID 36254394, 2022). "γ-H2AX is closely related to DNA repair in tumor cells after radiotherapy." (PMID 35812184, 2022). "The γ‐H2AX expression was significant higher in tumours in shNC+Iri." (PMID 35187743, 2022). "In a previous study, we showed in tumor tissues from HBV, HCV or alcohol-associated etiologies reduced levels of the DNA damage signaling molecule H2AX compared to peritumoral and control tissues, a profile also reported during the progression of control to tumor tissue in the breast." (PMID 35954469, 2022). "The γ-H2AX-positive tumor cell area within the tumor region for mice treated with 195mPt-BP (1.66 ​± ​0.4%) was 4.6-fold higher than 195mPt-cisplatin (0.36 ​± ​0.1%), 11-fold higher than radio-inactive Pt-BP (0.15 ​± ​0.1%), and 32-fold higher than saline control (0.05 ​± ​0.04%)." (PMID 33490949, 2021). "In addition, the number of γ-H2AX lesions was also increased in the NPs group compared to radiotherapy alone group, indicating that NPs significantly increased DNA damage to tumor cells by radiotherapy." (PMID 34372869, 2021). "Moreover, an inverse correlation between VAV2 and γ-H2AX levels in ESCC tumor samples existed (Spearman r = −0.431, P = 0.015)." (PMID 34462423, 2021). "As a consequence, it was speculated that the downregulation of γ-H2AX in P+ group in vivo may be due to the long-term chronic damage of periodontal pathogens, resulting in the downregulation of tumor cells’ response to DNA damage." (PMID 34660289, 2021). "By immunohistochemical staining of Sirt3, p-ATM, p-Chk2 and γ-H2AX in each group of tumor tissues, it was also found that the activation of γ-H2AX was more pronounced in Sirt3 knockdown group, and the radiation-induced activation of p-ATM was significantly attenuated." (PMID 34405009, 2021). "Proliferation and cell damage were evaluated as Ki-67 and γ-H2AX values in tumor tissues." (PMID 33777779, 2021).